CFTR (CF transmembrane conductance regulator)
Diseases named in the same sentence as CFTR in open-access papers (continued):
Sharing a sentence is not in itself a finding about the gene and the disease.
cystic fibrosis (continued). "RNF5 is an E3 ubiquitin protein ligase, and RNF5-KD significantly reduces AMFR-mediated ubiquitinylation of CFTR, a transmembrane conductance regulator in cystic fibrosis." (PMID 35741332, 2022). "Here, we bring together two previously developed resources of community-derived knowledge on cystic fibrosis, namely, the CandActCFTR database and the CFTR Lifecycle Map, to aid in the elucidation of modes of action for known active compounds." (PMID 36293229, 2022). "CF is caused by various mutations in the gene that codes for the cystic fibrosis transmembrane conductance regulator (CFTR) gene which encodes a cyclic adenosine monophosphate regulated chloride channel, responsible for chloride and bicarbonate secretion across epithelia cells." (PMID 35405954, 2022). "The marketing approval, about ten years ago, of the first disease modulator for patients with cystic fibrosis harboring specific CFTR genotypes (~5% of all patients) brought new hope for their treatment." (PMID 35650428, 2022). "Cystic fibrosis is a complex multisystem disorder caused by mutations in the gene encoding the cystic fibrosis transmembrane conductance regulator channel (CFTR) that is responsible for conducting chloride (Cl−) and bicarbonate (HCO3−) ions across the epithelia." (PMID 35455747, 2022). "Over the past decades, correctors and potentiators of the cystic fibrosis transmembrane conductance regulator (CFTR), a chloride ion channel causing cystic fibrosis when mutated, were developed to reduce the symptoms of the patients." (PMID 35456644, 2022). "Cystic fibrosis (CF, MIM# 219,700) is an autosomal recessive disease caused by pathogenic variants within the CFTR gene." (PMID 35365085, 2022). "Enhancing facilitated transport has been of interest for several diseases, most prominently with cystic fibrosis transmembrane conductance regulator (CFTR) and cystic fibrosis but also with the glutamate transporters and amyotrophic lateral sclerosis." (PMID 35216120, 2022). "This test has proven very reliable for predicting responses to Cystic Fibrosis Transmembrane conductance Regulator (CFTR) and has become the first personalized organoid medicine application for cystic fibrosis patients in the Netherlands." (PMID 35936888, 2022). "The plasma membrane (PM) stability of the cystic fibrosis transmembrane conductance regulator (CFTR), the protein which when mutated causes Cystic Fibrosis, relies on multiple interaction partners that connect CFTR to signaling pathways, including cAMP signaling." (PMID 35892592, 2022). "Other potentiators, like H-01 and A-04, P1, P2, P7 (from the Cystic Fibrosis Foundation’s CFTR Compound Program) and most notably ABBV-974 (; formerly GLPG-1837) clustered together in combinatorial profiling, suggesting a similar mode-of-action as VX-770." (PMID 35740997, 2022). "Cystic fibrosis is the most common life-threatening autosomal recessive disease in Caucasian populations, and it is caused by mutations in the cystic fibrosis transmembrane conductance regulator (CFTR) gene." (PMID 35268374, 2022). "CF is among the most common autosomal recessive diseases in humans and is caused by mutation of the cystic fibrosis transmembrane conductance regulator (CFTR) gene." (PMID 35912110, 2022). "Cystic fibrosis is the most common inherited disease in the Caucasian population, caused by mutations in the CF transmembrane conductance regulator (CFTR) gene; over 2,000 disease-causing CFTR mutations have been reported (CFTR2, 2021)." (PMID 35465025, 2022). "Amiloride and its analogues inhibit ENaC, as does CFTR, explaining the excessive sodium absorption in cystic fibrosis patients." (PMID 35626748, 2022). "More recently, RNF5 has been described as a quality control protein in the ER where it contributes to the clearance of misfolded proteins, including the F508del mutant cystic fibrosis transmembrane conductance regulator (CFTR)." (PMID 35406574, 2022).
cystic fibrosis (continued). "A look towards the future: what is the perspective of treatments as DNAse for patients with Cystic Fibrosis treated with CFTR modulators?" (PMID 35927765, 2022). "For most respondents, CFTR modulator therapies are the most likely to succeed in treating cystic fibrosis in the next 15 years, especially through the use of CFTR modulator combinations." (PMID 35268374, 2022). "CREB protein levels are reduced in human azoospermia testes, which is consistent with the protein’s down-regulation in cystic fibrosis mouse models and in CFTR-inhibited cultured Sertoli cells." (PMID 35725394, 2022). "Cystic fibrosis is a life-shortening genetic disorder that affects the cystic fibrosis transmembrane conductance regulator (CFTR) protein." (PMID 35276841, 2022). "The cystic fibrosis transmembrane conductance regulator (CFTR), which is mutated in cystic fibrosis, forms clusters that are cholesterol dependent and become incorporated into long-lived platforms during hormonal stimulation." (PMID 35060604, 2022). "Several studies have reported DED in patients with cystic fibrosis, suggesting the potential influence of CFTR in tear secretion." (PMID 36209216, 2022). "This work describes an optimized assay to determine CFTR drug responses in people with cystic fibrosis, using nasal-airway organoids that are generated from 2D differentiated epithelial monolayers." (PMID 35922154, 2022). "During recent decades, the life expectancy of people with cystic fibrosis (pwCF) has increased dramatically, and treatment with cystic fibrosis transmembrane regulator (CFTR) modulators will likely contribute to further improvements." (PMID 36483264, 2022). "An example of pharmacoperones as a feasible therapeutic approach to ameliorate the effect of misrouting is the case of the misfolded ΔF508 CFTR chloride channel leading to cystic fibrosis." (PMID 36093106, 2022). "CF is caused by mutations of the gene encoding for the cystic fibrosis transmembrane conductance regulator protein (CFTR), a transmembrane anion channel expressed at the apical membrane of epithelial cells of the airway, the gastrointestinal tract, the pancreas, and the biliary and sweat ducts." (PMID 35741067, 2022). "However, during cystic fibrosis, a disease associated with opportunistic infections and mucosal barrier abnormalities due to mutations in cystic fibrosis transmembrane conductance regulator (CFTR), defective autophagy is associated with more severe disease." (PMID 37425656, 2022). "To show how the viewer operates, we used an individualized text mining workflow to create a sample data set with the use case of cystic fibrosis, based on the CFTR Lifecycle Map we previously curated." (PMID 36139119, 2022). "Over 400 variants in the cystic fibrosis transmembrane conductance regulator (CFTR) are CF-causing." (PMID 35396391, 2022). "The availability of highly effective CFTR modulators is revolutionizing the treatment of cystic fibrosis and drastically improving outcomes." (PMID 36294480, 2022). "WES data reanalysis was carried out to identify the molecular cause of the CFTR-RD features revealing a pathogenic variant in CFTR, c.1521_1523delCTT (Phe508Del, rs113993960, VCV000634837), the gene mutated in cystic fibrosis." (PMID 35627274, 2022). "CF is a monogenic disorder caused by mutations in the cystic fibrosis transmembrane conductance regulator (CFTR) gene, which encodes the CFTR protein, a chloride and bicarbonate channel responsible for regulation of ion transport across the apical membrane at the surface of certain epithelia." (PMID 35707985, 2022). "Most respondents also believe that fixing or replacing the CFTR gene will lead to a cure for cystic fibrosis within 15 years, with CRISPR-Cas9 being the most likely genetic tool for this purpose." (PMID 35268374, 2022).
cystic fibrosis (continued). "Cystic Fibrosis is an inherited disease affecting the CFTR (cystic fibrosis transmembrane conductance regulator) protein, marked by a vicious cycle of infection and inflammation which is highly deleterious for the patient’s lung function." (PMID 36614040, 2022). "A mutation in the CFTR gene that codes for the ABC transporter ABCC7 can cause cystic fibrosis." (PMID 35350751, 2022). "Within the last years, CFTR modulators that target the cystic fibrosis transmembrane conductance regulator (CFTR) ion channel have become available to many people with cystic fibrosis." (PMID 35529332, 2022). "The CFTR gene is a well-known gene with a strong genotype–phenotype correlation with cystic fibrosis (OMIM #219700)." (PMID 36003331, 2022). "CF, a major disorder associated with bronchiectasis, is caused by mutation of a gene called cystic fibrosis transmembrane conductance regulator (CFTR), and its dysfunction results in mucus retention and chronic infection with subsequent local airway inflammation." (PMID 35769905, 2022). "The authors would like to acknowledge Robert Bridges, the Rosalind Franklin University of Medicine, and the Cystic Fibrosis Foundation for the contribution of compounds to this work through the CFTR Chemical Compound Distribution Program." (PMID 35608904, 2022). "Spatial covariance analysis shows how each residue in the critical fold region of chloride channel CFTR, defective in cystic fibrosis patients, contributes to CFTR’s export from the endoplasmic reticulum and function in the cell." (PMID 35418593, 2022). "These nonredundant roles are exemplified by the consequences of genetic CFTR dysfunction and cystic fibrosis." (PMID 35608904, 2022). "Cystic fibrosis is a disease caused by the alteration of a single gene located on the long arm of chromosome 7—the CFTR gene (regulator of the transmembrane conductance of cystic fibrosis)." (PMID 36014883, 2022). "Cystic fibrosis is an autosomal recessive disease caused by mutations in the cystic fibrosis transmembrane conductance regulator (CFTR) gene and is characterized by impaired mucociliary clearance, recurrent respiratory infections, and progressive lung function decline, leading to early mortality." (PMID 35477313, 2022). "Individuals with cystic fibrosis suffer from severe respiratory disease due to a genetic defect in the cystic fibrosis transmembrane conductance regulator (CFTR) gene, which impairs airway epithelial ion and fluid secretion." (PMID 36293514, 2022). "Cystic fibrosis remains a potentially fatal disease, but it has become treatable as a chronic condition due to some CFTR-rescuing drugs that, when used in combination, increase in their therapeutic effect due to a synergic action." (PMID 36293130, 2022). "Highly effective cystic fibrosis transmembrane conductance regulator (CFTR) modulators have led to dramatic improvements in lung function in many people with cystic fibrosis (PwCF)." (PMID 36142862, 2022). "Cystic fibrosis lung disease is another life-threatening chronic inflammatory lung disease with various mutations in the cystic fibrosis transmembrane conductance regulator (CFTR), which assists in the regulation and clearance of mucus." (PMID 35280995, 2022). "Molecular structures reveal how drugs rectify structure and function of the most common CFTR mutant in cystic fibrosis." (PMID 36264792, 2022). "Cystic fibrosis is the most common life-limiting autosomal recessive disease in Caucasian populations due to variants in the CF Transmembrane Conductance Regulator (CFTR) gene." (PMID 35997436, 2022). "Before the introduction of CFTR-modulators, literature regarding cystic fibrosis highlighted the unpredictability of CF." (PMID 35062937, 2022). "A cystic fibrosis transmembrane conductor regulator (CFTR) gene modulating triple therapy combining elexacaftor-tezacaftor-ivacaftor (Trikafta) has been recently discovered." (PMID 36284811, 2022).
cystic fibrosis (continued). "Cystic fibrosis is an autosomal recessive disorder caused by mutations in the Cystic Fibrosis Transmembrane Conductance Regulator (CFTR) gene, located in the long arm of chromosome 7, which encodes the CFTR protein, important for maintaining electrolyte balance." (PMID 36102402, 2022). "Although defective CFTR leads to cystic fibrosis, dysregulation of CFTR can promote or suppress cancer progression." (PMID 36230654, 2022). "Over the past decade, a new class of drugs called CFTR (cystic fibrosis transmembrane conductance regulator) modulators have shown to be able to improve clinical outcomes in patient with Cystic Fibrosis." (PMID 35525974, 2022). "Measurement of drug efficacy of the CFTR-modulating treatments (ivacaftor, lumacaftor plus ivacaftor and genistein plus curcumin) in rectal organoids from cystic fibrosis patients and correlation with in vivo effects." (PMID 34147034, 2022). "Cystic fibrosis is the most common life-limiting autosomal recessive genetic disorder in Caucasians and is caused by variants in the cystic fibrosis transmembrane conductance regulator (CFTR) gene." (PMID 36294279, 2022). "Cystic fibrosis (OMIM: #219700), a congenital disease with an autosomal recessive mode of inheritance, is caused by mutations in the CFTR gene (OMIM: *602421; cytogenetic location: 7q31.2)." (PMID 35468710, 2022). "As part of a cystic fibrosis drug discovery programme, a high‐throughput screen of approximately 150,000 small molecules was performed to identify new CFTR potentiators." (PMID 34644413, 2022). "This macrocycle is a useful tool to study the CFTR/14-3-3 interaction and the potential of molecular glues in cystic fibrosis therapeutics." (PMID 35739107, 2022). "Cystic fibrosis is a genetic disease, where a mutation of a protein called cystic fibrosis transmembrane conductance regulator (CFTR) leads to an alteration of ion transport across the cellular membrane and the to the production of thick, sticky mucus that clogs the airways and traps microorganisms." (PMID 36293502, 2022). "Cystic fibrosis, a multi-organ genetic disease, is characterized by abnormal function of the cystic fibrosis transmembrane conductance regulator (CFTR) protein, a chloride channel at the apical membrane of several epithelia." (PMID 35163362, 2022). "The interaction of KRT8 with the CFTRΔF508 mutant, the most common mutation in patients with cystic fibrosis, at nucleotide-binding domain 1 (NBD1) inhibits the translocation of CFTR to the cell surface." (PMID 36231117, 2022). "If CFTR plays a significant role in neuronal health, a neuronal phenotype should be evident in cystic fibrosis patients." (PMID 36462404, 2022). "It is widely accepted that 5–10% of normal, full-length CFTR transcripts should be sufficient to prevent a severe cystic fibrosis form." (PMID 35627274, 2022). "Ivacaftor is FDA- and EMA-approved in selected cystic fibrosis patients harboring class III CFTR variations localized inside and outside ATP-binding sites." (PMID 36142670, 2022). "CF is caused by a mutation in a gene that encodes a chloride-conducting transmembrane channel termed the cystic fibrosis transmembrane conductance regulator (CFTR), located in the long arm of chromosome 7 (7q31)." (PMID 36568105, 2022). "CFTR is largely studied in relation to cystic fibrosis, however, impaired function of this ion channel has been associated with more severe or difficult to treat asthma." (PMID 36206293, 2022). "The combinations of the cystic fibrosis transmembrane conductance regulator (CFTR) correctors lumacaftor and tezacaftor with the potentiator ivacaftor were the first CFTR modulator drugs approved for the treatment of patients with cystic fibrosis homozygous for the common F508del mutation." (PMID 35207295, 2022). "Since the discovery of the CFTR gene, the expectation of developing treatments that can substantially increase the quality of life or even cure cystic fibrosis patients is growing." (PMID 35268374, 2022).
cystic fibrosis (continued). "Decreased ASL height also contributes to increased mucus viscosity (KE5), a phenomenon that is well described in cystic fibrosis, where CFTR defect results in decreased ASL height, leading to decreased MCC (KE7) and subsequent mucus plugging." (PMID 35295103, 2021). "This interesting property of curcumin to cross-link selected proteins is also relevant in cystic fibrosis, where the compound cross-links cystic fibrosis channel (CFTR) dimers leading to their activation." (PMID 33937075, 2021). "Cystic fibrosis is caused by two defective copies of the cystic fibrosis transmembrane conductance regulator gene CFTR and is considered the most common severe monogenic disease inherited in an autosomal recessive fashion among the population of Western European ancestry." (PMID 34680949, 2021). "Previous study reported that FDA-approved drug ivacaftor targets cystic fibrosis transmembrane conductance regulator (CFTR) to treat cystic fibrosis, and CFTR has been indicated to facilitate glioma progression." (PMID 34046412, 2021). "Single amino acid mutations in the 140 kDa, twelve transmembrane domain CFTR protein disrupt its proper folding such that all CFTR protein is degraded by ERAD leading to cystic fibrosis." (PMID 34555015, 2021). "In autosomal dominant polycystic kidney disease (ADPKD), kidney cyst growth requires the recruitment of CFTR (cystic fibrosis transmembrane conductance regulator), the chloride channel that is defective in cystic fibrosis." (PMID 34445719, 2021). "In cystic fibrosis, defective biogenesis and activity of the cystic fibrosis transmembrane conductance regulator (CFTR) leads to airway dehydration and impaired mucociliary clearance, resulting in chronic airway infection and inflammation." (PMID 33859562, 2021). "Loss‐of‐function mutations in CFTR cause the lethal genetic disease cystic fibrosis." (PMID 34382377, 2021). "CFTR therapeutics are generally considered safe and are well-tolerated, although this pertains to its use in cystic fibrosis patients." (PMID 34367053, 2021). "For example, cystic fibrosis transmembrane conductance regulator (CFTR) mutant Δ508 is ubiquitinated and internalized by endocytosis, which causes cystic fibrosis." (PMID 34948259, 2021). "Pseudomonas aeruginosa gradually increases its presence in the CF airways after the pathological phenotypes of CFTR malfunction appear more obviously with the increased age of the CF sufferers." (PMID 34867864, 2021). "Cystic fibrosis (CF; OMIM: 219700) is an autosomal recessive disease caused by the loss-of-function mutation of the cystic fibrosis transmembrane conductance regulator (CFTR) gene encoding the CFTR protein." (PMID 34575636, 2021). "Cystic fibrosis is a genetic disorder marked by a multi-organ disease due to a defect in the CFTR (cystic fibrosis transmembrane conductance regulator) protein, a transmembrane ion channel." (PMID 33925199, 2021). "All of this to provide future opportunities for therapeutic targeting to improve the management and quality of life of patients with cystic fibrosis or CFTR-RD." (PMID 33807548, 2021). "Cystic fibrosis is a disease caused by autosomal recessive defects resulting in functional abnormalities of the cystic fibrosis transmembrane conductance regulator (CFTR) protein." (PMID 34868882, 2021). "This is a descriptive cross-sectional study that aims to determine the distribution of the CFTR causing variant in a group of patients at a cystic fibrosis center in southern Brazil, as well as to describe causing variants that are treatable with mutation-specific drugs." (PMID 34874053, 2021). "Cystic fibrosis is a recessive genetic disease characterized by mutations in the gene encoding the CF transmembrane conductance regulator (CFTR), a phosphorylation-regulated ion channel responsible for conducting chloride and bicarbonate ions across epithelial cell membranes." (PMID 33441643, 2021).